PRR9 (proline rich 9)
Tractability: No criterion of Open Targets' tractability assessment is met for any kind of drug.
Gene: Protein-coding gene on chromosome 1 (153,217,584 to 153,219,310, forward strand). Ensembl gene ENSG00000203783.
Subcellular location (Human Protein Atlas): Cytosol; Nucleoplasm; Vesicles
Genetic constraint (gnomAD): Loss-of-function variants: 15 observed, 9.64 expected, observed/expected ratio (o/e) 1.56, 90% interval 1.01 to 1.94. That is too few expected variants to judge how well the gene tolerates losing a copy. Missense variants: 141 observed, 138.15 expected, observed/expected ratio (o/e) 1.02, 90% interval 0.89 to 1.17. Synonymous variants: 48 observed, 52.77 expected, observed/expected ratio (o/e) 0.91, 90% interval 0.72 to 1.16.
Homologues: Orthologues: chimpanzee PRR9 (97% identical), macaque PRR9 (96% identical), mouse Prr9 (78% identical), pig PRR9 (78% identical), rat Prr9 (73% identical), rabbit PRR9 (71% identical). Paralogues in human: SPRR2G (29% identical), SPRR3 (26% identical), SPRR1A (24% identical), SPRR1B (24% identical), SPRR4 (23% identical), KPLCE (22% identical), LCE2B (16% identical), LCE2C (16% identical), LCE2D (16% identical), LELP1 (16% identical), LCE3D (15% identical), LCE3E (15% identical), and 8 more.
Diseases named in the same sentence as PRR9 in open-access papers:
PRR9 is named in the same sentence as 2 diseases in open-access papers, as found by Europe PMC text mining. Sharing a sentence is not in itself a finding about the gene and the disease. The quoted sentences say what the papers report.
Arrhythmia (2 papers, 2014 to 2024). Any cardiac rhythm other than the normal sinus rhythm. "Consistent with previous reports, both null mutants, elf3-1 and elf3-4, displayed arrhythmia with reduced levels of CCA1::LUC and LHY::LUC and high levels of TOC1::LUC, GI::LUC, PRR7::LUC, and PRR9::LUC, compared to Bay-0." (PMID 24867215, 2014).
psoriasis (1 paper, 2020). An autoimmune condition characterized by red, well-delineated plaques with silvery scales that are usually on the extensor surfaces and scalp. "The CHi-C data showed multiple, robust interactions between the psoriasis-associated regions at the LCE genes, including from within the 32-kb LCE3C/B-del region, and genes downstream in the EDC that included IVL, LOR, PRR9 and SPRR genes, over a distance of ~ 600 kb." (PMID 32366252, 2020).